TBX2 (T-box transcription factor 2)
Diseases named in the same sentence as TBX2 in open-access papers (continued):
Sharing a sentence is not in itself a finding about the gene and the disease.
tumor (53 papers, 2006 to 2025). "While NDRG1 was contributing to tumour suppression following loss of TBX2/CoREST, a number of other target genes (potentially novel TSGs) were likely involved in this phenotype and therefore warranted further investigation." (PMID 35687133, 2022). "The mechanistic interpretation that most easily agrees with observations in human tumor biology is that Omb/TBX2 overexpression causes a type of epithelial-mesenchymal transition (EMT)." (PMID 25344916, 2014). "Together, these results suggest that TBX2 is strongly implicated in malignant tumor progression by promoting an aggressive mesenchymal tumor phenotype." (PMID 22844464, 2012). "ChIP analysis and cell-based reporter assays further revealed that TBX2 directly represses transcription of E-cadherin, a tumor suppressor gene, whose loss is crucial for malignant tumor progression." (PMID 22844464, 2012). "Since tumor tissues used for expression profiling are subjected to histology and only included if they contain a reasonable percentage of tumor cells it is unlikely that the observed correlations are due to expression of TBX2 in tumor associated stroma." (PMID 22844464, 2012). "Tbx2 loss showed stage-specific effects on tumor development." (PMID 41705258, 2025). "Importantly, the observed identical MFI2, MUC12, UBE2H, and TBX2 mutations were each observed in a patient-matched tumor pair and an additional tumor sample." (PMID 32604718, 2020). "Whilst the anti-senescence activity of TBX2 has been extensively studied, it has remained unclear whether TBX2 can also contribute to tumor invasion, as the clinical association of TBX2 gene amplification with invasive epidermal tumors would suggest." (PMID 22844464, 2012). "Functional studies have shown that depletion or dominant-negative inhibition of TBX2 leads to the reactivation of p21 and muscle-specific genes, impairing tumor growth." (PMID 40508013, 2025). "This repression has been shown to involve complex mechanisms by which TBX2 co-opts transcription factors and recruits co-repression complexes to the promoters of these tumour suppressor genes." (PMID 39912718, 2025). "The T-box transcription factor TBX2 is markedly upregulated in tumor cells across both major RMS subtypes—ARMS and ERMS." (PMID 40508013, 2025). "In xenograft models, TBX2 inhibition completely blocked tumor development, underscoring its oncogenic potential in RMS." (PMID 40508013, 2025). "Although studies have shown the role of TBX2 as a tumor suppressor gene, there is some evidence correlating the overexpression of TBX2 in NSCLC." (PMID 37324026, 2023). "This direct interaction inhibits circulating tumor cell proliferation and induces senescence in the tumor cells by regulating the expression of the transcription factor TBX2 and the cyclin-dependent kinase inhibitor p21." (PMID 36497078, 2022). "Together, this would argue for TBX2 interaction with histone-methyltransferases such as was shown for repression of NDRG1 in tumor cells." (PMID 33731112, 2021). "In our current study, we identified TBX2 as being markedly over-expressed in a subset of tumor samples in 20 out of 37 data sets available from Oncomine by COPA analysis." (PMID 31897234, 2020). "Through COPA analysis, we found that TBX2 was significantly over-expressed in a subset of tumor samples in 20 out of 37 available data sets (gene rank, top 10%; fold change > 2; P < 1x 10-4)." (PMID 31897234, 2020). "TBX2 serves as a potent oncogene in RMS and many other cancers when overexpressed and thus, understanding the deregulation of TBX2 through the PRC2-TBX3-TBX2 axis offers insight in new approaches to inhibit tumor growth of RMS and additional cancers." (PMID 30979887, 2019). "Together, these results strongly suggest that TBX3 does not appear to confer oncogenic properties in RMS cells and appears instead to function as a tumor suppressor by repressing TBX2." (PMID 30979887, 2019).
tumor (continued). "Next, we assessed the effect of DNA copy number alterations on TBX2 expression levels using an ANOVA analysis in the NRC tumor dataset (n = 218, GSE85047)." (PMID 30451831, 2018). "We then expanded this analysis to additional targets including cystatin 6 (CST6), a cysteine protease inhibitor which functions as a tumor suppressor and has been identified as a repression target of TBX2 through a mechanism involving EGR1." (PMID 29719592, 2018). "Taken together, our data suggest a possible important role for TBX2 as hitherto unrecognized transcriptional regulator in NB tumor development." (PMID 30451831, 2018). "We first analyzed the CCLE database and found that NB was the tumor entity exhibiting the most frequent gains for the TBX2 locus, the highest expression and lowest methylation levels." (PMID 30451831, 2018). "Suppression of E-cadherin also leads to activation of an Ankyrin G-dependent transcription pathway involving NRAGE/TBX2 repression of the pro-apoptotic tumor suppressor p14ARF." (PMID 29069783, 2017). "Together these data suggest that the mechanism through which CST6 induces apoptosis is due to its inhibition of LGMN activity and that TBX2 drives tumor growth through maintenance of LGMN activity." (PMID 24742492, 2014). "We found that TBX2 directly represses E-cadherin transcription and promotes malignant tumor progression by imparting an aggressive mesenchymal tumor phenotype." (PMID 22844464, 2012). "We confirmed endogenous TBX2 overexpression in three ER-positive luminal tumor lines (MCF7, MDA-MB361, and BT-474) that have previously been shown to harbor TBX2 gene amplifications." (PMID 22844464, 2012). "Inappropriate activation of TBX2 in cancer is thought to contribute to early tumor progression by its ability to over-ride senescence and therefore maintain tumor growth." (PMID 22844464, 2012). "Efficient TBX2 knockdown was achieved in MDA-MB-435 tumor cells by stable transduction with lentiviruses expressing TBX2-specific shRNA (shTBX2), and in MDA-MB-157 cells by transient transfection with TBX2-specific siRNAs (siTBX2)." (PMID 22844464, 2012). "To further investigate how aberrant overexpression of TBX2 contributes to malignant tumor progression, we analyzed the metastatic potential of TBX2-depleted MDA-MB-435 tumor cells." (PMID 22844464, 2012). "While it has been shown that overexpression of TBX2 can bypass senescence, a failsafe mechanism against cancer, its potential role in tumor invasion has remained obscure." (PMID 22844464, 2012). "Another strategy to inhibit TBX2 could be through microRNA replacement therapy, for example through restoring the tumour suppressors miR-7 and miR-331–3p, known negative regulators of TBX2." (PMID 39912718, 2025). "In addition, TBX2 was shown to promote cisplatin resistance in endometrial carcinoma by inhibiting ferroptosis, a form of regulated cell death, and accelerating tumour growth in cisplatin-treated mice." (PMID 39912718, 2025). "TBX2 is a developmental transcription factor that is overexpressed in numerous cancers where it functions as a powerful oncogene by driving tumour progression, invasion and metastasis, and conferring tumour drug resistance." (PMID 39912718, 2025). "It is worth noting that TBX2 and TBX3 have been implicated in conferring tumour drug resistance, and because PO can target them, it may be associated with reduced tumour drug resistance." (PMID 40717225, 2025). "Besides, ectopic expression of TBX2/3 contributed to chemotherapy resistance, DNA polyploidy and tumor proliferation." (PMID 38413457, 2024). "Specifically, amplified TBX2 in BC might acts as a mediator of cell senescence and thus promotes tumor progression via repressing tumor suppressors such as p16 or p21 in cell cycle (TBX1)." (PMID 37860520, 2023). "Besides, several tumor-related genes, like VEGFA, TBX2, and TGFB1, were also enriched in the high-risk group." (PMID 36203430, 2022).
tumor (continued). "Taken as a whole, these results demonstrated that LINC00111 possesses tumour-suppressive properties by regulating both TBX2 and p21WAF1/CIP1 expression, and as such has important ramifications for cancer cell survival when targeted for repression by the TBX2-CoREST complex." (PMID 35687133, 2022). "In conclusion, the findings indicated that TBX2 tumor cell expression could be identified as a novel prognostic predictor in GC clinical treatment, which may improve the current TNM system in terms of patient counselling." (PMID 32231721, 2020). "Positive staining of the TBX2 protein was mainly located in the nuclei of tumor cells." (PMID 32231721, 2020). "Our results suggested that TBX3 functions as a tumor suppressor in ARMS by repression of TBX2." (PMID 30979887, 2019). "Of further interest, the highest expression levels for TBX2 were observed in NB cell lines and primary tumors compared to other tumor entities, based on the online pan-cancer analysis in the CCLE database (cancer cell lines) and R2 platform (primary tumors and normal tissues)." (PMID 30451831, 2018). "Moreover, overexpression of TBX2 in human lung and skin cancer models, although inhibitory to cell growth, has been shown to promote the resistance of tumor cells to the anti-cancer drug cisplatin." (PMID 22844464, 2012). "Since TBX2 is aberrantly amplified with high prevalence in a number of aggressive human epidermal cancers, or, as we found, can be induced by TGFß, a promoter of metastatic tumor progression, these findings are of potential high clinical relevance." (PMID 22844464, 2012). "Importantly, we found that inhibition of TBX2 also abolished tumor cell migration, invasion and profoundly diminished the capacity of MDA-MB-435 cancer cells to form pulmonary metastases in a xenograft in vivo mouse model." (PMID 22844464, 2012). "Importantly, TBX2 inhibition abolished tumor cell invasion and the capacity to form lung metastases in a Xenograft mouse model." (PMID 22844464, 2012). "Moreover, epithelial ß-catenin and ZO1 not only were increased in levels, but also properly localized to the cell membrane in TBX2-depleted MDA-MB-435 tumor cells." (PMID 22844464, 2012). "However, the potential role of TBX2 in malignant tumor progression has remained unclear." (PMID 22844464, 2012). "TBX2 achieved this by recruiting HDAC1 to the promoters of the myogenic regulatory factors, MyoD and myogenin, and the tumour suppressors, p21Cip1, p14ARF and PTEN." (PMID 39912718, 2025). "The transcription factors TBX2 and NFIB were highly activated in the relapsed tumor subgroups (Subgroups 4 and 5), potentially playing profound roles in transcriptional regulation in the recurrence of HCC tumors." (PMID 40018995, 2025). "As TBX2 is the main marker of Th1 cells, these results indicate a positive relationship between ACAA1 and Th1 cell infiltration in the tumor stroma." (PMID 33194642, 2020). "And TBX2 and TBX3 over-expressions has been elucidated to induce the tumor growth and metastasis, functioning as downstream target gene of Wnt/beta-catenin and pRb pathway through the suppression of p14ARF, p21CIP1, NDRG1 and E-cadherin." (PMID 33447348, 2020). "Instead, we found that TBX3 acts as a tumor suppressor in RMS, largely due to its repression of TBX2." (PMID 30979887, 2019). "Comparison of primary tumor and metastasis cells from the same patient revealed up‐regulation of RELN and TBX2,TBX4 and TBX5 genes and down‐regulation of several HOXD genes." (PMID 29542868, 2018). "The distribution of TBX2 and TBX5 was examined in formalin-fixed paraffin-embedded tissue sections from tumor-free regions of the lung." (PMID 30425966, 2018). "At the molecular level, we discovered that expressions of several tumor suppressor genes, including p21, p27, phosphatase with tensin homology (PTEN) and E-Cadherin, were increased dramatically after TBX2 knockdown in above NPC cells." (PMID 28881763, 2017).
tumor (continued). "Collectively, our results imply that TBX2 over-expression promotes NPC cell proliferation and invasion, possibly via silencing several key tumor suppressor genes." (PMID 28881763, 2017). "Data in the literature on the overexpression of TBX2 and TBX3 in tumor samples and tumor cell lines vary depending on the reference sample chosen and on the molecular category inspected (DNA, RNA, or protein) but tend to lie in the range of 1.5 to 10-fold." (PMID 25344916, 2014). "Previous studies have reported that T-box genes/proteins such as TBX2 and TBX3 are overexpressed in several neoplasms." (PMID 25287937, 2014). "Here we demonstrate that TBX2 is a strong cell-autonomous inducer of the epithelial-mesenchymal transition (EMT), a latent morphogenetic program that is key to tumor progression from noninvasive to invasive malignant states." (PMID 22844464, 2012). "Collectively, our work suggests that TBX2 is a key driver of malignant tumor progression through induction of EMT and tumor cell invasiveness." (PMID 22844464, 2012). "This revealed that tumor cells in MBMs not only exhibited significantly upregulated tumorigenesis and maintenance genes (e.g., MET and TBX2), but also expressed neural differentiation markers (e.g., NRG3, NELL1, NCAM1, ADNP) and cell adhesion molecules (e.g., CDH1, PRKCA)." (PMID 41284647, 2025). "Once TBX2 or TBX3 expression is dysregulated, it may be involved in the formation of tumor stemness." (PMID 38965548, 2024). "This property of TBX2 and TBX3 makes it to be an important regulator during the tumor process." (PMID 38965548, 2024). "It is therefore plausible that TBX2 could reposition SIRT3 to reduce promoter-specific and/or global H4K16 acetylation, a phenomenon which has been reported in multiple tumour types." (PMID 35687133, 2022). "Additionally, the detection of hypermethylated PIK3R5, TBX2 and TWIST1 in all four tumor tissues suggests the specificity of these biomarkers for the four TCGA cancers screened in this manuscript, and their potential as therapeutic targets." (PMID 33143142, 2020). "TBX2, which has thus far not been studied in NB, is most highly expressed in this tumor entity as compared to other tumor entities and also strongly upregulated in mouse neural crest-derived MYCN overexpressing NB46." (PMID 30451831, 2018). "This analysis underscored canonical tumor promoting genes (e.g. cell cycle promoting genes such as CDK1 and BUB1) that were up-regulated in LUADs relative to normal lung tissues and concomitantly downstream of down-regulated TBX2 with the same gene-network." (PMID 28978111, 2017). "Finally, TBX2 expression is positively correlated with GATA3, HAND2, and PHOX2B expression levels as well as with those of other potential CRC genes important in development in a NB tumor cohort (n = 283)." (PMID 30451831, 2018). "Additionally, whereas control non-target shRNA expressing MDA-MB-435 tumor cells formed spheroids with extensive protrusions in three-dimensional (3D) Matrigel cultures, reflective of their invasive nature, knockdown of TBX2 resulted in the formation of round, non-invasive spheres." (PMID 22844464, 2012). "Comparative genomic hybridization array (aCGH) analysis showed no significant increases in TBX2 gene copy numbers in MDA-MB-435 and MDA-MB-157, suggesting that overexpression of TBX2 in these tumor cell lines is not due to gene amplification." (PMID 22844464, 2012).
cancer (49 papers, 2006 to 2025). A tumor composed of atypical neoplastic, often pleomorphic cells that invade other tissues. "TBX2 is an antisenescence T-box family transcription repressor implicated in embryonic development and cancer." (PMID 34819350, 2021). "In development and in the wide range of cancers where it is overexpressed, Tbx2 has been implicated in proliferation, senescence bypass, and cell invasion." (PMID 34819350, 2021). "Aberrant TBX2 expression is likely to be just one of many pathways leading to loss of CST6 in cancers." (PMID 24742492, 2014). "TBX2 was first linked to cancer through its ability to facilitate senescence bypass in Bmi-/- mouse embryo fibroblasts and was found to be a potent immortalizing gene downregulating Cdkn2a (p19ARF, p14ARF in humans)." (PMID 24742492, 2014). "Tbx2 also has been implicated in various cancers as a pro-proliferative factor and may play a similar role in GRP2/MP3." (PMID 41154668, 2025). "Additionally, TBX2 has been implicated in conferring resistance to anti-cancer drugs resulting in poor therapeutic outcomes." (PMID 39912718, 2025). "TBX2 is strongly associated with development of heart and limbs and cancer." (PMID 34064060, 2021). "Part of this may be attributed to the induction of polyploidy and resistance to anti-cancer drugs (cisplatin), which can be caused by TBX2 overexpression." (PMID 26579496, 2015). "In addition, recent studies report that TBX2 expression has been implicated in human cancer." (PMID 32231721, 2020). "Although TBX2 has some properties of a lineage dependency factor, overexpression and amplification of TBX2 has been associated with poor prognosis in various other cancer entities and TBX2 is also a well-known developmental gene acting in various tissues including neural crest." (PMID 30451831, 2018). "Thus, apart from chromosome 17q23 amplification, TBX2 induction by TGFß may represent a novel mechanism underlying the aberrant overexpression of TBX2 in invasive cancers." (PMID 22844464, 2012). "This minireview discusses TBX2’s involvement in cancer signalling, its regulatory partners, and its impact on cancer progression and resistance to therapy." (PMID 39912718, 2025). "This creates a mutual activation loop among Tbx2, Tbx3, and Tbx5, with the notable exception that Tbx3 represses Tbx2, as was reported for cancer cells." (PMID 41278973, 2025). "Circ_0060927 acted as a molecular sponge for miR-331-3p, thereby upregulating its downstream target gene, T-Box transcription factor 2 (TBX2), to drive cancer progression." (PMID 40936702, 2025). "TBX2 plays diverse and critical roles in cancer biology from promoting tumourigenesis by driving cell proliferation, senescence bypass and apoptosis inhibition, to driving EMT, invasion and migration." (PMID 39912718, 2025). "Together, these studies suggest that, at the very least in some cancers, there is a positive feedback loop between the Wnt/β-catenin pathway and TBX2 which drives invasion and migration." (PMID 39912718, 2025). "For example, the PI3K/AKT and Wnt/β-catenin signalling pathways play key roles in the EMT process, and both these pathways were shown to converge on TBX2 in some cancers." (PMID 39912718, 2025). "The overexpression of TBX2 frequently correlates with clinical stage and overall poor patient survival and contributes to several cancer hallmarks including proliferation, migration, metastasis, resistance to cell death and conferring drug resistance." (PMID 39912718, 2025). "There are, therefore, examples of drugs that can exert anti-cancer activity, in part, through inhibiting multiple components of the TBX2 oncogenic pathway." (PMID 39912718, 2025). "A similar mechanism was reported in RMS where TBX2 drives cancer progression by inhibiting myogenesis in favour of promoting proliferation." (PMID 39912718, 2025).